TOX3 (TOX high mobility group box family member 3)
Description:
Transcriptional coactivator of the p300/CBP-mediated transcription complex. Activates transactivation through cAMP response element (CRE) sites. Protects against cell death by inducing antiapoptotic and repressing pro-apoptotic transcripts. Stimulates transcription from the estrogen-responsive or BCL-2 promoters. Required for depolarization-induced transcription activation of the C-FOS promoter in neurons. Associates with chromatin to the estrogen-responsive C3 promoter region.
Synonyms: CAGF9; TNRC9
Tractability: PROTAC: ubiquitination databases record sites on it.
Gene: Protein-coding gene on chromosome 16 (52,436,417 to 52,547,802, reverse strand). Ensembl gene ENSG00000103460.
Subcellular location: Nucleus
Subcellular location (Human Protein Atlas): Nucleoplasm; Cytosol
Gene Ontology:
Molecular function: chromatin binding; phosphoprotein binding; protein binding; protein homodimerization activity; transcription coactivator activity; chromatin DNA binding
Biological process: negative regulation of neuron apoptotic process; positive regulation of transcription by RNA polymerase II; regulation of apoptotic process; regulation of transcription by RNA polymerase II
Cellular component: cytosol; nucleoplasm; nucleus
Genetic constraint (gnomAD): Loss-of-function variants: 13 observed, 43.96 expected, observed/expected ratio (o/e) 0.3, 90% interval 0.19 to 0.47. The upper end of that interval is the gene's LOEUF score, 0.47, which puts it in group 2 of 6, group 1 being the genes least tolerant of losing a copy. Missense variants: 579 observed, 620.69 expected, observed/expected ratio (o/e) 0.93, 90% interval 0.87 to 1. Synonymous variants: 265 observed, 245.46 expected, observed/expected ratio (o/e) 1.08, 90% interval 0.98 to 1.2.
Homologues: Orthologues: macaque TOX3 (99% identical), chimpanzee TOX3 (99% identical), pig TOX3 (97% identical), mouse Tox3 (95% identical), rat Tox3 (95% identical), dog TOX3 (94% identical), tropical clawed frog tox3 (79% identical), rabbit TOX3 (78% identical), zebrafish tox3 (65% identical), Caenorhabditis elegans hmg-3 (10% identical), Caenorhabditis elegans hmg-4 (10% identical). Paralogues in human: TOX (43% identical), TOX4 (34% identical), TOX2 (34% identical), UBTF (15% identical), HMGXB4 (14% identical), SMARCE1 (14% identical), SP100 (14% identical), SSRP1 (13% identical), HMG20B (11% identical), SP140 (10% identical), HMGB2 (10% identical), HMGB1 (9% identical), and 8 more.
Diseases named in the same sentence as TOX3 in open-access papers:
TOX3 is named in the same sentence as 57 diseases in open-access papers, as found by Europe PMC text mining. Sharing a sentence is not in itself a finding about the gene and the disease. The quoted sentences say what the papers report.
breast carcinoma (96 papers, 2007 to 2026). "Eight of the breast cancer-associated variants are intronic variants in the TOX3 gene, one is a intronic variant in the CASC16 gene, while the remaining one is located in the intergenic region between TOX3 and CASC16." (PMID 41180965, 2025). "For both ER+/- BC, TOX3 had a PIP of 1 in breast mammary tissue, supporting the notion that TOX3 causally impacts breast cancer etiology." (PMID 38515142, 2024). "It is worth noting that a minor allele of TOX3 has been widely reported to implicate in an elevated risk of breast cancer and be associated with the prognosis of patients." (PMID 34976002, 2021). "For example, TOX3 is highly expressed in breast cancer (particularly luminal breast cancer) and is associated with poor prognosis." (PMID 33743809, 2021). "Although TOX3 has been recognized as a susceptible gene in breast cancer for many years, its molecular mechanism in the pathogenesis of breast cancer is still poorly understood." (PMID 33716953, 2020). "The TOX3 gene plays a key role during the onset of breast cancer, and reproductive factors such as abortion are risk factors for breast cancer." (PMID 31454102, 2019). "Through literatures, it has been discussed that the mutation of TOX3 was associated with breast cancer susceptibility." (PMID 30924295, 2019). "They found 4 SNPs associated with a higher breast cancer risk, two of which, rs3803662 in TOX3 and rs2981579-A (FGFR2), are consistent with our findings." (PMID 31125336, 2019). "TOX3 polymorphisms and epigenetic regulation have been demonstrated in breast cancer and lung cancer respectively." (PMID 29285217, 2017). "The TOX3/LOC643714 locus on chromosome 16q12.1 was one of the first breast cancer regions identified through genome-wide association study (GWAS) in populations of European and East Asian origin." (PMID 27486757, 2016). "A significant association with TOX3 expression was observed in rs3803662 (p = 3.4e-7), a risk variant of breast cancer in European women, with the minor A allele associated with lower TOX3 expression." (PMID 27806084, 2016). "SNP rs4784227, a risk variant identified in Asian women, also showed a significant association with TOX3 expression (p = 0.004) with the minor T allele associated with increased risk of breast cancer and lower TOX3 expression." (PMID 27806084, 2016). "The minor allele of SNP rs3803662 has been shown to correlate with increased breast cancer risk and with lower expression of TOX3." (PMID 27806084, 2016). "A functional study following GWAS showed that the risk allele of rs3803662 and the mRNA level of TOX3 predicted adverse outcomes for breast cancer patients." (PMID 27806084, 2016). "The SNP rs4784227, a risk variant for breast cancer in Asian women, was also reported to alter TOX3 expression by disrupting enhancer function through FOXA1 affinity modulation." (PMID 27806084, 2016). "In Latinas, 4 (MAP3K1, ZMIZ1, FGFR2, and TOX3) of the 12 regions have been associated with breast cancer in 1497 cases and 3213 controls." (PMID 27814745, 2016). "This was consistent with earlier work where a linked disease-associated SNP was correlated with lower TOX3 mRNA in breast cancers." (PMID 25632947, 2015). "The ability of TOX3 to upregulate a number of genes implicated in breast cancer or mammary gland development, including TBX3, BMP7, and IL17RB, was confirmed by qRT-PCR in transiently transfected cells under estrogen-depleted conditions." (PMID 25632947, 2015). "ORs with 95% CI were used to assess the strength of association between TOX3 polymorphisms and breast cancer risk in fixed or random effect model." (PMID 26239137, 2015). "One of the identified regions, on chromosome 16q12.1, includes TOX3, a gene already associated with breast cancer risk." (PMID 25956309, 2015). "This is in sharp contrast to previous studies that indicated breast cancer susceptibility is associated with lower expression of TOX3." (PMID 25632947, 2015).
breast carcinoma (continued). "In general, our study proved that the T-rs3803662 and T-rs8051542 in TOX3 were correlated with elevated breast cancer risk in all genetic models." (PMID 26239137, 2015). "The associations of SNPs in TOX3 gene with breast cancer risk were investigated by some Genome-wide association studies and epidemiological studies, but the study results were contradictory." (PMID 26239137, 2015). "To determine if the expression of TOX3 was associated with a particular molecular subtype of breast cancer, we analyzed a publicly available microarray data set of primary human breast cancers." (PMID 25632947, 2015). "Using a common downstream primer and specific upstream primers that allowed us to distinguish these variants by PCR, the long form of TOX3 appears as the predominant mRNA in breast cancer cell lines and two primary breast tumors." (PMID 25632947, 2015). "Some GWASs and epidemiological studies have identified the associations of TOX3 polymorphisms with breast cancer susceptibility." (PMID 26239137, 2015). "In conclusion, the meta-analysis suggested that three SNPs in TOX3 were significantly associated with breast cancer risk in different populations." (PMID 26239137, 2015). "A subset of breast tumors also highly expresses TOX3, with poor outcome associated with high expression of TOX3 in luminal B breast cancers." (PMID 25632947, 2015). "In conclusion, this meta-analysis indicated that there were different associations between the 3SNPs in TOX3 gene and breast cancer risk in different ethnic groups or subtype tumor." (PMID 26239137, 2015). "The specific mechanism by which low-risk genetic variants confer breast cancer risk is currently unclear, with contradictory evidence on the role of single nucleotide polymorphisms (SNPs) in TOX3/LOC643714 as a breast cancer susceptibility locus." (PMID 24481062, 2014). "For BRCA2 carriers, SNPs at loci 10q26 (FGFR2) and 16q12.1 (TOX3) were associated with all subtypes of breast cancer." (PMID 25919761, 2014). "TOX3 maps to 16q12, a region commonly lost in breast cancers and recently implicated in the risk of developing breast cancer." (PMID 24069272, 2013). "It has also been shown that the effects of TOX3 expression and of the risk allele of rs3803662 in breast cancer is stronger in ER positive tumours." (PMID 24069272, 2013). "It has been suggested that rs3803662 (a C>T transition) in TOX3 was associated with an increased risk of breast cancer in both BRCA1 and BRCA2-mutation carriers and estrogen receptor (ER) positive patients." (PMID 24069142, 2013). "Recently, genetic polymorphism (rs3803662C>T) in TOX3 was reported to induce the risk of breast cancer." (PMID 24069142, 2013). "In particular, the breast cancer associations were limited to loci associated with estrogen receptor (ER)-negative breast cancer in the general population (6q25.1, 12p11 and TOX3)." (PMID 23544013, 2013). "Our rationale for performing this screen was that TOX3 maps to a known breast cancer susceptibility locus, which is also commonly a region of LOH in breast cancer." (PMID 24069272, 2013). "Whilst copy number changes of 16q12 are common in breast cancer, our data show that mutations of TOX3 are present at low frequency in tumours." (PMID 24069272, 2013). "Further evaluation of 18 loci associated with breast cancer susceptibility in the general population found that only the TOX3, LSP1, 2q35 and RAD51L1 loci were significantly associated with breast cancer for BRCA1 carriers." (PMID 23544013, 2013). "Other loci previously found to be associated with BRCA1 breast cancer risk include the 19p13 and 6q25.1 loci, TOX3 and CASP8." (PMID 22348646, 2012). "The only evident connection between TOX3 and breast cancer is that the gene has been implicated in breast tumor metastasis to bone." (PMID 22087758, 2011). "A positive association was also observed with rs3803662, near TOX3, which has also been associated with sporadic breast cancer risk." (PMID 21060860, 2010).
breast carcinoma (continued). "Women with any G allele of rs12443621 in TOX3 had 3% to 4% higher percent dense area than women homozygous for the A allele; the association was stronger in premenopausal women and breast cancer cases." (PMID 19232126, 2009). "The polymorphism rs12443621 in TOX3 was associated with percent dense area; women with at least one G allele (previously associated with increased breast cancer risk) had 3% to 4% higher densities than women with two A alleles." (PMID 19232126, 2009). "TOX3 is well-documented for its association with breast cancer through multiple SNPs." (PMID 41180965, 2025). "TOX3 has been widely recognized to be associated with breast cancer, and it has been suggested that it may be a modulator of estrogen receptor‐mediated gene expression." (PMID 39578713, 2024). "In addition, rs2981582 in FGFR2, rs16886165 in MAP3K1 and rs3803662 in TOX3 are associated with breast cancer in populations of European ancestry, and the first two were also associated with breast cancer in Uruguay." (PMID 33126731, 2020). "TOX3 was recently reported as a breast cancer susceptibility gene by large-scale GWAS." (PMID 32425888, 2020). "Furthermore, Park SL et al37 found that TOX3 rs3803662 C>T was significantly associated with the risk of breast cancer." (PMID 31454102, 2019). "TOX3 has been shown to protect neurons from cell death caused by stress originating in the endoplasmic reticulum and to be amplified and overexpressed in breast cancer, supporting a cancer-associated function." (PMID 31308487, 2019). "Ectopic expression of TOX3 is associated with tumor progression in breast cancer mouse model." (PMID 31757997, 2019). "In summary, the present study discovered for the first time that rs9933638/rs12443621 and rs3104746, the previously identified breast cancer susceptibility-related SNPs at the TOX3/LOC643714 locus, contributed to the individual's risk to lung cancer in the Southwestern Han Chinese population." (PMID 27486757, 2016). "Ectopic expression of TOX3 increased breast cancer cell proliferation, migration, and survival after exposure to apoptotic stimuli and were associated with tumor progression in a mouse model of breast cancer." (PMID 27806084, 2016). "It was in breast cancer associated TOX3 (rs10653661 according to dbSNP141)." (PMID 26822197, 2016). "Two TOX3 transcripts encoding proteins with distinct N-termini have been reported, and we found predominant expression of mRNA encoding the long form of TOX3 in normal breast tissue, breast cancer cell lines, and primary breast cancer." (PMID 25632947, 2015). "Conversely, loss of TOX3 from LumB BT474 breast cancer cells led to decreased proliferation." (PMID 25632947, 2015). "Hence, in order to resolve the conflict, we performed this meta-analysis of the associations between the TOX3 rs3803662, rs12443621 and rs8051542 polymorphism and breast cancer risk." (PMID 26239137, 2015). "In addition, these results can begin to shed light on the reported association of TOX3 expression and breast cancer metastasis to the bone, and point to TOX3 as a novel regulator of estrogen receptor-mediated gene expression." (PMID 25632947, 2015). "However, some TOX3 expressing tumors are associated with adverse outcome, and increased expression of TOX3 mRNA has been implicated in breast cancer metastatic to bone." (PMID 25632947, 2015). "However, only one of these genes, TOX3, has already been associated with breast cancer in other population-based studies." (PMID 25956309, 2015). "A breast cancer susceptibility locus has been mapped to the gene encoding TOX3." (PMID 25632947, 2015). "In this breast cancer case-control study among Chinese women, we assessed the association of breast cancer with five SNPs (rs8051542, rs12443621, rs3803662, rs4784227, and rs3112612) in the TOX3/LOC643714 locus to provide confirmatory replicative results of several studies in multiple populations." (PMID 24481062, 2014).
breast carcinoma (continued). "The specific mechanisms by which causative variants in TOX3/LOC643714 affect breast cancer risk remain unclear." (PMID 24481062, 2014). "This is the first study to determine the importance of TOX3 mutations in breast cancers." (PMID 24069272, 2013). "However, GWAS focused on a loci polymorphism at TOX3 gene that is associated with breast cancer survival, especially in estrogen receptor (ER) positive patients." (PMID 24069142, 2013). "In the present study we selected 2 sets of primary breast tumours and screened TOX3 for mutations in the entire coding region, to ascertain whether TOX3 mutations have a role in breast cancer." (PMID 24069272, 2013). "Furthermore, LSP1 and TOX3 mRNAs were targeted by miR196a-3p and miR196a-5p respectively, and these genes were also identified as novel breast cancer susceptibility markers." (PMID 21637771, 2011). "The association of mammographic density with rs12443621, if confirmed, may provide clues as to how variation in TOX3 influences breast cancer risk." (PMID 19232126, 2009). "The association with rs12443621 may provide clues as to how variation in TOX3 influences breast cancer risk." (PMID 19232126, 2009). "TOX3 contains a high mobility group box motif that suggests it is a transcription factor, but the specific mechanism by which variation in TOX3 affects breast cancer risk is unknown." (PMID 19232126, 2009). "We observed a stronger association in cases; it could be that cases have other environmental or genetic factors interacting with TOX3 to increase both mammographic density and breast cancer risk." (PMID 19232126, 2009). "Furthermore, TOX3 has been increasingly associated with human cancer, particularly breast cancer." (PMID 40328361, 2025). "This is in line with other studies suggesting these SNPs as risk-associated polymorphisms which may lead to a change in the affinity of FOXA1, as a distal enhancer, to TOX3 and thus change in TOX3 expression, which can eventually affect the risk of breast cancer." (PMID 31338012, 2019). "To determine the effects of genetic variants associated with breast cancer on regulating TOX3 expression, we applied a linear regression model and conducted eQTL analyses on 345 SNPs genotyped 500 kb upstream and 250 kb downstream of the TOX3 gene, using TCGA dataset." (PMID 27806084, 2016). "In the study, to test our hypothesis that the previously identified breast cancer risk-associated genetic polymorphisms at the TOX3/LOC643714 locus might contribute to lung cancer risk, 16 SNPs at the TOX3/LOC643714 locus were evaluated in a Han Chinese population based on a case-control study." (PMID 27486757, 2016). "Therefore, we performed an updated meta-analysis to aim to come up with the highest level of evidence for the associations between three SNPs in TOX3 gene and breast cancer risk among diverse ancestry populations and distinct tumor subtypes stratified by estrogen receptor (ER) or BRCA1/BRCA2." (PMID 26239137, 2015). "Although allele frequencies of 5q11.2/MAP3K1 rs889312 (like 16q12.1/TOX3 rs3803662) were substantially different between Europeans and Koreans, the rs889312 C allele was also significantly associated with increased risk of breast cancer (OR = 1.16; 95% CI = 1.06 to 1.27; Ptrend = 8.49 × 10-4)." (PMID 22452962, 2012). "Differences in panel performance influenced association signals, including breast cancer candidate loci such as FGFR2, TOX3, and ESR1." (PMID 41871294, 2026). "According to previous studies, TOX3 can promote the oncogenesis and development of breast cancer, colorectal cancer, and lung cancer through the MAPK, EMT, and Hippo‐related signaling pathways." (PMID 38463397, 2024). "The genes involved in the known three loci—FGFR2, CCND1 and TOX3—have been thoroughly discussed in relation to breast cancer." (PMID 35267517, 2022). "Lastly, SigMod missed some of the highest scoring breast cancer susceptibility genes in the dataset, like FGFR2 and TOX3." (PMID 33735170, 2021).